STIL (STIL centriolar assembly protein)
Description:
Immediate-early gene. Plays an important role in embryonic development as well as in cellular growth and proliferation; its long-term silencing affects cell survival and cell cycle distribution as well as decreases CDK1 activity correlated with reduced phosphorylation of CDK1. Plays a role as a positive regulator of the sonic hedgehog pathway, acting downstream of PTCH1. Plays an important role in the regulation of centriole duplication. Required for the onset of procentriole formation and proper mitotic progression. During procentriole formation, is essential for the correct loading of SASS6 and CPAP to the base of the procentriole to initiate procentriole assembly. In complex with STIL acts as a modulator of PLK4-driven cytoskeletal rearrangements and directional cell motility.
Synonyms: SIL; MCPH7
Tractability: PROTAC: UniProt records ubiquitination sites on it; ubiquitination databases record sites on it.
Gene: Protein-coding gene on chromosome 1 (47,250,139 to 47,314,892, reverse strand). Ensembl gene ENSG00000123473.
Subcellular location: Cytoplasm, cytosol; Cytoplasm, cytoskeleton, microtubule organizing center, centrosome, centriole; Cytoplasm, cell cortex
Subcellular location (Human Protein Atlas): Basal body; Centrosome; Nucleoplasm; Cytosol
Gene Ontology:
Molecular function: identical protein binding; protein binding
Biological process: centrosome duplication; mitotic spindle organization; positive regulation of centriole replication; positive regulation of G1/S transition of mitotic cell cycle; protein localization to centrosome; regulation of centriole replication; determination of left/right symmetry; embryonic axis specification; floor plate development; forebrain development; heart looping; in utero embryonic development; microtubule organizing center organization; multicellular organism growth; negative regulation of apoptotic process; neural tube closure; neural tube development; notochord development; positive regulation of spindle assembly; regulation of mitotic spindle organization; smoothened signaling pathway
Cellular component: centriole; centrosome; ciliary basal body; cytoplasm; procentriole replication complex; microtubule organizing center; cell cortex; cytosol
Genetic constraint (gnomAD): Loss-of-function variants: 43 observed, 96.5 expected, observed/expected ratio (o/e) 0.45, 90% interval 0.35 to 0.57. The upper end of that interval is the gene's LOEUF score, 0.57, which puts it in group 2 of 6, group 1 being the genes least tolerant of losing a copy. Missense variants: 1,293 observed, 1,525.3 expected, observed/expected ratio (o/e) 0.85, 90% interval 0.81 to 0.89. Synonymous variants: 460 observed, 534.68 expected, observed/expected ratio (o/e) 0.86, 90% interval 0.8 to 0.93.
Gene-disease validity (ClinGen):
ClinGen rates the evidence that STIL causes each of these diseases.
autosomal recessive primary microcephaly (autosomal recessive): Definitive. Autosomal recessive primary microcephaly (MCPH) is a rare genetically heterogeneous disorder of neurogenic brain development characterized by reduced head circumference at birth with no gross anomalies of brain architecture and variable degrees of intellectual impairment.
Homologues: Orthologues: chimpanzee STIL (98% identical), macaque STIL (95% identical), dog STIL (82% identical), pig STIL (77% identical), rabbit STIL (76% identical), mouse Stil (74% identical), rat Stil (71% identical), guinea pig STIL (63% identical), tropical clawed frog stil (42% identical), zebrafish stil (35% identical).
Diseases named in the same sentence as STIL in open-access papers:
STIL is named in the same sentence as 58 diseases in open-access papers, as found by Europe PMC text mining. Sharing a sentence is not in itself a finding about the gene and the disease. The quoted sentences say what the papers report.
microcephaly (24 papers, 2013 to 2025). A congenital or acquired developmental disorder in which the circumference of the head is smaller than normal for the person's age and sex. "We found that STIL, one of the primary microcephaly gene products, is associated with ARHGEF7 in dendritic spines and that knockdown of Stil resulted in a significant reduction in dendritic spines in neurons both in vitro and in vivo." (PMID 39851490, 2025). "SCL/TAL1 interrupting locus (STIL) gene is a crucial factor in centriole biogenesis, and dysfunction of this gene has been associated with abnormal brain development leading to microcephaly." (PMID 34485108, 2021). "STIL alteration has been implicated in lymphoblastic leukemia and microcephaly; however, the role of STIL in solid epithelial tumors stands least explored." (PMID 34485108, 2021). "A mutation in the CPAP TCP domain that causes microcephaly in humans has been shown to decrease the affinity of CPAP to STIL." (PMID 31115335, 2019). "So far, eight mutations in STIL have been described in 37 patients all showing severe microcephaly (−4 to −10 S.D.)." (PMID 29352115, 2018). "Another example of a gene mutated in primary microcephaly is SCL-interrupting locus protein (STIL), encoding a centriole-duplication factor that localizes to the procentriolar cartwheel region, a key structure in procentriole assembly." (PMID 25729350, 2015). "For example, mutations in the centriolar proteins CPAP and STIL cause a syndrome known as microcephaly, in which the brain is smaller than normal." (PMID 24052813, 2013). "Only a small set of conserved centriolar proteins is essential for centriole assembly and some of these proteins, like CPAP and STIL, have been linked to microcephaly in humans." (PMID 24052813, 2013). "CPAP (MCPH6) and STIL (MCPH7) are required for centriole assembly, but it is unclear how mutations in them lead to microcephaly." (PMID 24052813, 2013). "A homozygous missense mutation in STIL causes holoprosencephaly and microcephaly." (PMID 37627046, 2023). "Thus, microcephaly caused by STIL mutations can result from either too less centrosome duplication or too much centrosome amplification." (PMID 29352115, 2018). "A previous study revealed that STIL mutation could result in familial microcephaly." (PMID 35155425, 2022). "Moreover, STIL mutations in humans can lead to primary hereditary microcephaly and even cancer." (PMID 33858425, 2021). "This is further supported by the fact that many genes associated with microcephaly encode centrosome proteins (CPAP, CEP152, CEP135, STIL, and CDK5RAP2) involved in centriole biogenesis and centrosome maturation." (PMID 39412222, 2025). "All common mutations causing microcephaly are present in genes implicated in cell division (MCPH1, ASPM, CDK5RAP2, CENPJ, STIL, WDR62, and CEP152)." (PMID 37294214, 2023). "STIL has a role in centriole formation and has previously been described in rare cases of microcephaly." (PMID 25658757, 2015). "The results of our phylogenetic comparative analyses provide direct evidence that evolution of brain size is indeed linked to four microcephaly genes (ASPM, CDKRAP2, STIL, WDR62) in two mammalian clades, Glires and Euungulata." (PMID 24898820, 2014). "Although CPAP and STIL are known to bind each other, how they interact on a molecular level to form centrioles—and how this interaction is disrupted in microcephaly—is not well understood." (PMID 24052813, 2013). "We show that STIL overexpression induces centrosome amplification and aneuploidy, leading to senescence, apoptosis, and impaired proliferation in mouse embryonic fibroblasts, and microcephaly with increased perinatal lethality and shortened lifespan in mice." (PMID 39466849, 2024). "Also, mutations in STIL that reside in the CPAP and SAS6 interacting motifs have also been identified in patients with microcephaly, although the significance of these alterations remains to be determined." (PMID 31115335, 2019).
microcephaly (continued). "Alternatively, microcephaly in MCPH7 patients can result from a decrease of STIL levels." (PMID 29352115, 2018). "Therefore, both accumulation and impairment of STIL protein levels during cell cycle affect centriole regulation and result in microcephaly." (PMID 29352115, 2018). "Many genes have been implicated in the development of microcephaly (summarized inTable 1) includingASPM,MCPH1,CDK5RAP2,CEP152,CENPJ,WDR62,STIL,CASC5,CEP135,ZNF335,PHC1,CDK6, with many of them contributing to centrosome and spindle protein dysfunction during mitosis." (PMID 26535115, 2015). "Cumulatively, these findings reinforce the importance of CPAP and STIL in centriole formation, and suggest that one reason for the development of microcephaly may be defects in the proper formation of centrioles." (PMID 24052813, 2013). "Indeed, when we created a partial knockdown of STIL, we were able to mimic another feature of microcephaly, which is a preferential effect in the CNS compared with other tissues." (PMID 24153002, 2013). "However exon skipping was only partial in the patient analyzed, suggesting some residual activity of STIL, and providing an explanation for the fact that this mutation is compatible with life and the idea that MCPH7 microcephaly can result from a decreased STIL activity." (PMID 29352115, 2018). "Decreased levels of RNA of a variety of genes involved in cell cycle progression and microcephaly including Microcephalin, CDK5RAP2, CASC5, ASPM, CENPJ, STIL, CEP135, and CDK6 was also observed." (PMID 29276699, 2017). "A number of microcephaly genes have been identified, including ASPM, microcephalin/BRIT1, CDK5RAP2/Cep215, CENPJ/CPAP, SIL/STIL, WDR62, and NDE1 (refs 3, 4, 5)." (PMID 27553190, 2016). "In vivo, in addition to induction of microcephaly, impaired skin stratification and perinatal lethality as previously reported for mice constitutively overexpressing PLK4 already, constitutive overexpression of STIL led to a shortened lifespan." (PMID 39466849, 2024). "To determine whether estradiol could regulate the seven currently known microcephaly genes (ASPM, CENPJ, CEP152, CDK5RAP2, MCPH1, STIL and WDR62), we conducted a search of the potential ERE (estrogen response element) sites in gene promoter regions." (PMID 26123139, 2015). "The overarching pattern of selection on microcephaly loci is therefore a consistent signature of positive selection across all eutherian mammals, perhaps with the exception of STIL, but with relatively little evidence of clade-specific differences in overall rates of evolution." (PMID 24898820, 2014).
breast cancer (12 papers, 2020 to 2025). A primary or metastatic malignant neoplasm involving the breast. "NMUR1 and NCAM1 are novel key disease-causing genes for luminal A breast cancer, and STIL is a novel key disease-causing gene for basal-like breast cancer." (PMID 33066779, 2020). "We identified NMUR1 and NCAM1 as novel key genes associated with the development, progression, and prognosis of luminal A breast cancer, and STIL as a novel key gene associated with the prognosis of basal-like breast cancer." (PMID 33066779, 2020). "Prior studies have suggested that high sTIL levels may be associated with worse outcomes in ER + HER2- breast cancer." (PMID 40114292, 2025). "Multiple studies have found that metaplastic breast cancer frequently expresses PD-L111,13,14 and tends to have higher sTIL incidence." (PMID 41038871, 2025). "Changes in STIL and SAS6 levels have been linked to several subtypes of breast cancer, such as TNBC, luminal breast cancer, and HER2-positive breast cancer." (PMID 38606093, 2024). "The relationship between sTIL levels and prognosis across different molecular subtypes in breast cancer, and its value in prediction and evaluating treatment warrant further clarification." (PMID 38420013, 2024). "In summary, we identified NMUR1 and NCAM1 as novel key genes associated with the development, progression, and prognosis of luminal A breast cancer, and STIL as a new target with the prognosis of basal-like breast cancer." (PMID 33066779, 2020). "Of the key genes unique to basal-like breast cancer, the expression levels of only CDC7, KIF18A, STIL, and CKS2 were associated with patient survival time (P < 0.05)." (PMID 33066779, 2020). "Our survival analysis showed that low expression of STIL statistically affects the overall survival of patients with basal-like breast cancer." (PMID 33066779, 2020). "Therefore, the sTIL level is now regarded as one of the most significant findings in the histopathologic examination of breast cancer and is recommended by international guidelines to be incorporated into the pathology report." (PMID 37648694, 2023). "Thus, we predict that promoting STIL expression could represent a novel modality to improve the treatment of basal-like breast cancer." (PMID 33066779, 2020). "Several studies have shown that a high level of sTIL is more common and predictive of a positive long-term prognosis in TNBC than in other types of breast cancer." (PMID 34680500, 2021). "Furthermore, low sTIL levels and negative ER expression were all linked with poor DFS, indicating their potential as prognostic markers, and providing a holistic view of the complex prognostic landscape of breast cancer." (PMID 38420013, 2024).
lung carcinoma (7 papers, 2018 to 2025). "Intriguingly, the concordant expression of STIL with SLUG displayed an especially high correlation in patients with metastatic lymph nodes (R = 0.76), suggesting that there is a strong association of the HIF1α-STIL-SLUG axis in lung cancer specimens." (PMID 35365182, 2022). "Thus, STIL can serve as a potential diagnostic marker for early lung cancer detection, and a promising therapeutic target for lung cancer treatment." (PMID 35365182, 2022). "There has been accumulating evidence that many types of tumors have high expression levels of STIL, including lung cancer, where its expression is markedly elevated." (PMID 39718123, 2025). "Our study provides mechanistic insights into previously observed CNAs in NSCLC and establishes a novel link between STIL overexpression and lung cancer carcinogenesis." (PMID 39727708, 2024). "Since brain is one of the most common sites of distant metastasis of lung cancer, we also examined STIL expression in brain metastases derived from lung cancer." (PMID 35365182, 2022). "Our results showed that STIL was up-regulated in multiple types of cancers, displaying the most significant increase in lung cancer patients." (PMID 35365182, 2022). "Together, our results indicate that STIL depletion significantly blocks the oncogenic properties of lung cancer cells." (PMID 35365182, 2022). "STIL showed the highest T/N ratio (3.5) among the studied genes; this was found in patients with lung cancer, and was even higher than the T/N ratio (1.5) of PLK4 in these patients." (PMID 35365182, 2022). "Taken together, our data strongly support the idea that STIL modulates lung cancer metastasis in vivo and its high-level expression is associated with poor survival of lung cancer patients." (PMID 35365182, 2022). "STIL protein levels in both cytoplasm and nucleus were significantly up-regulated in primary lung cancers compared with the normal lung tissues." (PMID 35365182, 2022). "Compared with normal lungs, STIL protein intensity was significantly elevated in the primary lung cancers and metastatic lymph node groups." (PMID 35365182, 2022). "Our results showed that the HIF1α intensity was positively correlated with the expression of STIL (Pearson’s co-efficient, R = 0.54) in lung cancer specimens." (PMID 35365182, 2022). "However, the precise mechanisms by which STIL controls lung cancer cell migration need to be further studied." (PMID 39735672, 2025). "Interestingly, STIL dysregulation has been reported in several human diseases, including microcephaly and cancers of the lungs, colorectum, urinary bladder, liver, and breast." (PMID 39727708, 2024). "Given that STIL is up-regulated in lung cancer and associated with worse prognosis, we first examined its oncogenic properties in two NSCLC cell lines, NCI-H1299 and NCI-H2009, which expressed high levels of STIL mRNA." (PMID 35365182, 2022). "Because STIL is also elevated in metastatic cancers, we next examined whether excess STIL could affect lung cancer cells migration and invasion." (PMID 35365182, 2022). "STIL mRNA level was significantly increased in brain metastases relative to primary lung cancers." (PMID 35365182, 2022). "Our findings indicate that STIL promotes tumor metastasis through the HIF1α-STIL-FOXM1 axis, and highlight the importance of STIL as a promising therapeutic target for lung cancer treatment." (PMID 35365182, 2022). "Similar results were also observed in STIL-knockdown NCI-H1299 and CL1-3 cells, suggesting that the effects of STIL knockdown on migration and invasion are independent of the lung cancer cell line used." (PMID 35365182, 2022).
autosomal recessive primary microcephaly (6 papers, 2013 to 2022). "The structure and function of STIL is described followed by an account of two phenotypes that have been associated with STIL dysfunction, autosomal recessive primary microcephaly (MCPH), and cancer." (PMID 29352115, 2018). "Autosomal primary recessive microcephaly (MCPH) is a disorder in neurogenesis caused by at least nine genes, six of which encode centrosome components (CEP63, CEP135, CEP152, CDK5RAP2/Cnn, CPAP /MCPH6, and STIL/MCPH7) and two encode proteins associated with spindle poles (ASPM and WDR62)." (PMID 30687396, 2018). "Autosomal Recessive Primary Microcephaly (MCPH) is one of those, for which seven loci (MCPH1-MCPH7) with the corresponding genes (MCPH1, WDR62, CDK5RAP2, CEP152, ASPM, CENPJ, and STIL) have been reported so far." (PMID 24148351, 2013).